IL6 (interleukin 6)
Diseases named in the same sentence as IL6 in open-access papers (continued):
Sharing a sentence is not in itself a finding about the gene and the disease.
cancer (continued). "The expressions of Bcl-2, IL-6, AKT, and P38 were significantly increased in the cancer tissues than in normal tissues while Bax level was significantly increased in non-cancerous tissue than in cancer tissue." (PMID 38072891, 2024). "Interestingly, we found that in the absence of cancer cells, although BCG or VPM vaccines induced an inflammatory cytokine response (induction of tnfa, il1b and il6), this was not translated into a marked innate cellular response." (PMID 39114912, 2024). "VEGF-A, TNF-α, CCL2, IL-6, and IFN-γ plasma levels were significantly higher in the Cancer TIF1-γ-DM group, especially those without any anticancer treatment, than those in the non-cancer TIF1-γ-DM and HC groups." (PMID 36357631, 2023). "To further investigate the connection between STAT1, STAT3 and said cytokines in drug resistance, we have treated cells (EP and LP) with cytokine-neutralized (IL-6, IL-10 and IL-1β) MDSC supernatant (in presence or absence of these cytokines), keeping untreated cancer cells as a control." (PMID 38304256, 2023). "• Inflammatory cytokines released by cancer cells.• Since stimulation by IL-6 and TNF-α induces bone-resorbing multinucleated giant cells, it is possible that some mechanisms of the bone-resorptive effects of IL-6 are not mediated by the RANK/RANKL pathway." (PMID 36626519, 2022). "Inhibition of some SASP elements, such as IL-6, C-X-C motif chemokine receptor 2 (CXCR2), IGFBP7 prevents senescence, and the lack of senescence may promote cancer development." (PMID 36232388, 2022). "However, our results showed that, according to the present protocol, cancer induction with DMH and/or NFRFP consumption does not modify serum concentrations of IFNγ, IL-6, IL-10, IL-12p70, MCP-1, and TNF-α." (PMID 34444868, 2021). "In a prior MESA study comparing the predictive value of GlycA and other inflammatory biomarkers, GlycA had a significantly predictive value comparable to hsCRP, IL-6, and D-dimer, if not superior, for total death, CVD, chronic inflammatory-related severe hospitalization and death, and total cancer." (PMID 33765041, 2021). "Furthermore, the pro-inflammatory cytokines of cancer patients including TNF-α, IL-6, and IL-2R were higher than those of patients without cancer." (PMID 34277701, 2021). "Nevertheless, in the scenario of cancer-related inflammation, we could not detect a robust reduction in IL-6 and CRP levels in the patients with cancer and cachexia after n-3 supplementation." (PMID 35174197, 2021). "Whilst we demonstrated that E6-mediated STAT3 phosphorylation required IL-6 autocrine/paracrine signalling, we do not know how E5 and E7 induce STAT3 phosphorylation, and whether or not this contributes to cancer development." (PMID 32899142, 2020). "Finally, by using a cytokine array, we verified that the release of other chemokines and interleukins, such as IL6, IL8, CCL2, CCL5, known to be involved in crosstalk between CAF and cancer cells, was not statistically different between CAF-S1 and CAF-S4." (PMID 31964880, 2020). "Active MCs contributed to aggravate inflammation reaction and induced colitis-related cancer by releasing the classical pro-angiogenic and pro-inflammatory factors including VEGF, FGF-2, PDGF, and IL-6, and nonclassical pro-angiogenic factors proteases including tryptase and chymase." (PMID 32209121, 2020). "Moreover, whereas we identified the effects of the overall inflammatory mediators on cancer incidence through DII, we did not observe the effects of individual inflammatory markers such as hs-CRP, IL-1β, IL-4, IL-6, IL-10 or (TNF)-α." (PMID 31652856, 2019). "In the proximal area, the expression levels of Tnfa and Il6 in the AOM/DSS group were significantly higher than those in the control group, suggesting drug-induced inflammation, although there was no macroscopic dysplasia or cancer in the area." (PMID 31484999, 2019).
cancer (continued). "Although many evidences confirmed a key role of IL-6 cascades in regulating the growth of malignant cells in preclinical studies, anti-IL6 or anti-IL6R mAbs have not demonstrated clinical efficacy in several cancer types." (PMID 32039001, 2019). "Levels of pro-inflammatory cytokines, IL-6 and IL-8, and anti-apoptotic protein, XIAP were measured by real-time PCR whereas the secreted IL-8 was quantitated by ELISA in TLR4-transient knockdown cancer cells with or without CpdA treatment." (PMID 29486738, 2018). "Due to the fact that IL-6 does not activate AKT in HT-1080 cells, it is likely that different cell lines or different cancers may activate different pathways in response to IL-6." (PMID 27531896, 2016). "IL-6R was detected in the cytoplasm and plasma membrane of almost all the cancer cells and observed in harmony with that of IL-6 in almost all the OSCC cells of the IL-6 high expression group, but not or weakly in the negative and low expression group (data not shown)." (PMID 25761055, 2015). "In addition, no changes in IL6 expression were observed in lysates from Tibialis anterior at both mRNA and protein level, indicating that both cancer cachexia and BCAA supplementation impact circulating IL6 levels without affecting local IL6 production in skeletal muscle." (PMID 40448398, 2025). "However, analysis in vitro may not represent the full biological effects of IL6 and BMP2 in vivo, as any interaction between them to promote cancer will be more complex in vivo." (PMID 38468450, 2024). "Besides, we observed an IL-6-induced proliferation in R-TMX cells, which has been reported in cancer cells that do not respond to estrogen; this induction could be regulated through the epidermal growth factor receptor (EGFR)." (PMID 39201674, 2024). "However, it did indicate that a combination of CRP, IL‐6, YKL‐40, CEA and CA 19‐9 can identify a subgroup of patients with nonspecific signs and symptoms of cancer who will develop cancer, and that they have a very poor prognosis if all biomarkers are elevated." (PMID 36440611, 2023). "This study included both pro‐inflammatory (IL‐1B, IL‐6, IL‐8, IL‐12 (p40, p70), TNF‐α, and IFN‐γ), and anti‐inflammatory (IL‐4, IL‐6, IL‐10, TGF‐β), peripheral cytokine blood serum markers with no significant findings evident between cancer survivors and matched controls." (PMID 37751068, 2023). "BJOE at ≤5 mg/ml was nontoxic to carcinoma cell lines, but could significantly inhibit WT/LMV-MT HBV replication and HBs/e/c antigen expression in a dose-dependent manner by upregulating interleukin-6 (IL-6), demonstrating that it possesses moderate anti-HBV activity." (PMID 37560319, 2023). "However, it is not clear whether the IL‐6/STAT3 pathway is regulated by the canonical Wnt/β‐catenin pathway in the malignant progression of CRC and other cancers." (PMID 34997691, 2022). "Finally, we did not observe a correlation between the levels of the inflammatory markers CRP or IL-6 and DELFI score in cancer-free individuals, consistent with the notion that cancer-specific fragmentation is not affected by the presence of acute or chronic inflammatory conditions." (PMID 34417454, 2021). "However with the exception of TGF-β, we found no consistent significant increases in IL-10, IL-4, Il-13, Il-6, GM-CSF, G-CSF, or VEGF in the blood that could account for the failure across cancer patients." (PMID 31462392, 2019). "Moreover, BTG2 over‐expression inhibits interleukin‐6 (IL‐6) expression through downregulation in the STAT3 pathway, as well as inhibiting reactive oxygen species (ROS) generation in the JAK2‐STAT3 signalling pathway; thus it has a negative effect on cancer cell growth." (PMID 29656435, 2018).
cardiovascular disease (856 papers, 2005 to 2026). "A novel pathogenic mechanism in cardiovascular disease (CVD) is the interaction between IL-6 and clonal hematopoiesis of indeterminate potential, CHIP, that involve the ten-eleven translocation-2 gene, a molecule with role in epigenetics." (PMID 41543641, 2026). "The severity of cardiovascular disease is linked to C-reactive protein, interleukin 6, and C-type natriuretic peptide levels, stressing the need for a sensitive sensor that can detect these biomarkers at ultralow levels in real time." (PMID 41752974, 2026). "CRP is a risk marker for future cardiovascular diseases (CVDs), and IL-6 and SAA are regarded as risk markers and even mediators for CVD." (PMID 40332485, 2025). "As a result, individuals who have the greatest initial levels of hs-CRP should be the main focus for reducing the risk of cardiovascular disease by inhibiting IL-6 signaling." (PMID 39844544, 2025). "RA is linked to an increased risk of developing comorbid conditions, where IL-6 is also directly involved, including cardiovascular diseases, infections, osteoporosis, depression, neoplasia, anaemia, and higher mortality rates." (PMID 40700294, 2025). "The Stepwise analysis identified IL-6 as the most significant predictor of cardiovascular disease risk, suggesting its pivotal role in subclinical vascular inflammation among obese individuals with T2DM." (PMID 40944271, 2025). "Acute exercise-induced elevation of IL-6 is beneficial, but prolonged resting IL-6 elevation leads to an increased risk of cardiovascular disease and metabolic inflammation." (PMID 40869331, 2025). "Crucially, excessive and dysregulated IL-6 production is a risk factor for various diseases and disorders (e.g., cardiovascular disease) and often correlates with symptom severity (including pain intensity and declines in physical and cognitive function)." (PMID 40740426, 2025). "Studies indicate that elevated IL-6 levels associated with chronic stress can act as mediators of chronic inflammation, contributing to the development of metabolic and cardiovascular diseases while also reducing immune activity." (PMID 39857306, 2025). "IL-6, a well-established pro-inflammatory cytokine, has been linked to the pathophysiology of cardiovascular disease, particularly in AF patients." (PMID 40744929, 2025). "IL-6 is a key player in chronic inflammation and has been implicated in fibrosis, autoimmune disorders, and cardiovascular diseases." (PMID 41373438, 2025). "For systemic risk assessment, elevated CRP levels, when combined with IL-6, serve as significant predictors of cardiovascular disease." (PMID 40418274, 2025). "For instance, monoclonal antibodies against IL-6, such as ziltivekimab, are under development with the aim of mitigating cardiovascular disease risk." (PMID 40141381, 2025). "The overall decrease in hs-CRP levels is likely equal to the impact of preventing IL-6 signaling in lowering cardiovascular disease risk." (PMID 39844544, 2025). "Although CRP has been traditionally used as a marker of systemic inflammation in cardiovascular diseases, IL‐6 is more directly implicated in myocardial inflammation pathways relevant to HCM progression." (PMID 41377766, 2025). "In T1D, IL‐6 has been associated with cardiovascular disease in a cross‐sectional study, and in a smaller prospective study (n ≈ 200), we previously observed a potential association between IL‐6 and all‐cause and cardiovascular mortality." (PMID 40619914, 2025). "Roghani’s study provides evidence of an association between elevated serum IL-6 levels and cardiovascular disease." (PMID 41010664, 2025). "IL-6, another important marker of inflammation, appears to be independently associated with a higher incidence of cardiovascular diseases in RA patients." (PMID 41010664, 2025). "Inflammatory markers like white blood cell (WBC), C-reactive protein (CRP), and interleukin-6 (IL-6) are strongly linked to cardiovascular disease." (PMID 40190468, 2025).
cardiovascular disease (continued). "Regarding IL-6 reduction, this parameter is very well-known to be associated with cardiovascular disease and mortality in CKD patients." (PMID 40864045, 2025). "Pro-inflammatory cytokines such as TNF, IL-1β, and IL-6, secreted by monocytes, enhance their migratory potential towards tissue sites of inflammation and are associated with an increased risk of cardiovascular disease in patients with CKD." (PMID 38558798, 2024). "It’s worth mentioning that follow-up studies have associated a median reduction of 0.16 pg/ml in IL-6 levels with a reduced hazard ratio of 1.44 in cardiovascular diseases and lower adiposity measurements." (PMID 38178093, 2024). "In European (Italian) patients with stage 2–5 CKD, high serum IL-6 was associated with a history of cardiovascular disease and predicted incident cardiovascular events, and this relationship was accompanied by the G174C polymorphism in the IL-6 gene." (PMID 38473905, 2024). "An increased expression of the fibrinolysis inhibitor serpine-1 (PAI-1) and Interleukin-6 (IL-6) indicated a pro-inflammatory milieu, especially in the vascular system, a phenomenon linked to aging-related cardiovascular pathologies." (PMID 39273272, 2024). "A recent study found that individuals with elevated IL-6 levels after 5 years had a higher independent risk of cardiovascular disease (CVD) at 10 years compared to those with lower levels." (PMID 39202593, 2024). "In summary, both IL-6 and IL-1β are integral to the inflammatory processes that underlie cardiovascular diseases." (PMID 39057626, 2024). "A study using proteomic analysis of biomarkers of cardiovascular disease also confirmed that the IL-1β/TNF-α/IL-6/CRP pro-inflammatory pathway was significantly associated with women suffering from angina pectoris combined with CMVD." (PMID 38836066, 2024). "IL-6 is a critical pro-inflammatory cytokine implicated in various disorders, including cardiovascular diseases and inflammation." (PMID 39202588, 2024). "We now know that previously reported associations between CRP and cardiovascular disease were likely driven by IL-6 signalling." (PMID 38951047, 2024). "Multiple prospective studies and meta-analyseshave confirmed that, there was an association between IL-6 levels and futurerisks of cardiovascular disease." (PMID 39139413, 2024). "Fasting triglycerides and CRP, synthesized by the liver in response to IL-6, are associated with cardiovascular disease in people living with HIV." (PMID 39529759, 2024). "Interleukine-6 (IL-6), also an important marker of inflammation, is independently associated with major adverse cardiovascular disease." (PMID 39469122, 2024). "The included studies showed that elevated IL-6 levels are associated with worse outcomes in patients with cardiovascular diseases." (PMID 39057626, 2024). "Previous reports have demonstrated that inflammatory mediators such as IL6 increase CHIP-comorbid risk to cardiovascular disease." (PMID 38573824, 2024). "Multiple meta-analyses have shown that IL-6 is significantly associated with all-cause mortality in multiple cardiovascular diseases." (PMID 37966667, 2023). "IL-6 is a pro-inflammation cytokine that has been implicated in the pathogenesis of cardiovascular diseases." (PMID 37047522, 2023). "Blacks, for whom cardiovascular disease is a leading cause of death, had higher concentrations of IL-6, CRP, and fibrinogen than Whites." (PMID 37623156, 2023). "IL-6, as an upstream marker of inflammation, is independently associated with the risk of major adverse cardiovascular disease events, MI, HF, and cancer mortality stable coronary heart disease." (PMID 37047468, 2023). "Systemic inflammation and circulating cytokines, such as interleukin 1, interleukin 6 and tumor necrosis factor α, are associated with cardiovascular diseases." (PMID 37900562, 2023).
cardiovascular disease (continued). "Shift work induced circadian misalignment has also been linked to elevated serum CRP levels, BP, interleukin-6 and tumour necrosis factor-α and increased cardiovascular disease risk." (PMID 37925459, 2023). "This can also cause an increased inflammatory (IL-6) response due to altered autonomic nervous system activity, which is associated with an increased risk of cardiovascular disease." (PMID 37910162, 2023). "Inflammatory markers, such as C-reactive protein (CRP) and interleukin-6 (IL-6), are associated with an increased risk of cardiovascular disease (CVD) events." (PMID 37908957, 2023). "All studies found a correlation between angiogenic factors, IL-6, and cardiovascular disease risk factors." (PMID 37887854, 2023). "Interleukin-6 (IL-6) stimulates chronic inflammation and regulates the expression of C-reactive protein and cardiovascular disease risk biomarker." (PMID 37273529, 2023). "IL-6 is a pro-inflammatory peptide associated with various aspects of cardiovascular disease, but its role in AS in particular is still under debate." (PMID 37509127, 2023). "It is supposed that short-term IL-6 signaling protects and preserves heart tissue in response to acute injury; moreover, long-term IL-6 signaling or overproduction of the IL-6R protein plays a causal role in cardiovascular disease." (PMID 37047468, 2023). "The present study results corroborated previous findings on the link between increased serum IL-6 and the risk of cardiovascular diseases." (PMID 35887619, 2022). "Excess plasma IL-6 levels trigger the release of C-reactive proteins by hepatocytes, which indicate the levels of chronic inflammation and the risk of cardiovascular disorders." (PMID 35267958, 2022). "Prior research conducted in Germany, Italy, and South Africa established that the IL-6 G174C SNP was associated with increased circulating levels of IL-6, as well as an increased risk of developing cardiovascular disease and mortality in CKD patients." (PMID 35887619, 2022). "According to the findings of a meta-analysis of 42 studies involving 15,145 cases and 21,496 controls, the C allele of the IL-6 G174C SNP was associated with an increased risk of cardiovascular disease in Caucasians." (PMID 35887619, 2022). "Although there is a growing body of evidence associating IL-6 with cardiovascular disease, most are indirect observations from case–control studies or sub-group analyses." (PMID 36028849, 2022). "Serum C-reactive protein (CRP) and interleukin-6 (IL-6) are known inflammation biomarkers and independent predictors of cardiovascular disease (CVD) and mortality risk in dialysis patients." (PMID 35458220, 2022). "The rs1800795 polymorphism in the promoter region of IL6 gene is one of the most widely analyzed in cardiovascular diseases." (PMID 36337884, 2022). "The plasma IL-6 concentration was proposed to be a T2DM and cardiovascular disease marker associated with an inflammatory state, and increased systemic IL-6 concentrations have been correlated with increased fat mass in both rodent models and obese humans." (PMID 35648976, 2022). "IL-6 levels have been shown to increase with aging and are associated with increased cardiovascular disease risk." (PMID 35222077, 2022). "In uremic patients, among a variety of inflammatory biomarkers, IL-6 has been demonstrated to be a robust predictor of cardiovascular disease and all-cause mortality." (PMID 33536542, 2021). "The presence of Flavonifractor was found in association with circulating inflammatory markers (i.e., interleukin-6, interleukin-8, interleukin-1β), which were linked to cardiovascular disease." (PMID 33809103, 2021). "For example, associations between IL-6 and muscle loss were significantly stronger in populations with cardiovascular disease compared to their disease-free peers." (PMID 34830593, 2021).